CCL5 (C-C motif chemokine ligand 5)
Diseases named in the same sentence as CCL5 in open-access papers (continued):
Sharing a sentence is not in itself a finding about the gene and the disease.
gastric cancer (continued). "TMEM92-AS1 has been shown to promote gastric cancer progression by targeting CCL5, and further study has shown that it may affect leukocytes via regulation of the expression of granulocyte colony-stimulating factor in gastric cancer tissues." (PMID 36324509, 2022). "MTT assays verified that overexpression of TMEM92‐AS1 can promote the proliferation of gastric cancer cells, knockdown of CCL5 can inhibit proliferation, and overexpression of TMEM92‐AS1 can accelerate the sluggish proliferation rate caused by knockdown of CCL5." (PMID 33247987, 2021). "The CCR5/CCL5 axis plays a crucial role in gastric cancer (GC) progression." (PMID 32630699, 2020). "In addition, TAMs promote the epigenetic silencing of gelsolin through DNA methyltransferase 1 activity induced by CCL5/CCR5/STAT3 signaling in gastric cancer cells." (PMID 31892854, 2020). "The data revealed that gastric cancer cells may have an influence on the level of CCL5 secretion by CD4+ T-cells." (PMID 32098198, 2020). "The role of CCL5 in the progression of gastric cancer was investigated by Sugasawa and co-workers." (PMID 32098198, 2020). "Gastric cancer cells stimulate CD4+ T lymphocytes to secrete CCL5 and they may also induce Fas-FasL-mediated apoptosis of CD8+ T lymphocytes using CCL5." (PMID 24523569, 2014). "Therefore, CCL5 may be a potential target for future treatment strategies for gastric cancer patients." (PMID 39003350, 2024). "Finally, CCL5 blockade significantly compromised gastric cancer progression." (PMID 22205974, 2011). "Because CCL5/CCR5 is one the central axis of activation for DNA repair from damage caused by CDDP and DNA repair is one of the most important mechanisms of CDDP resistance, we hypothesized that CCR5 inhibition by MVC could enhance the action of CDDP in gastric cancer platinum-resistant cells." (PMID 39827154, 2025). "Through the reciprocal effects of VEGFC and CCL5, CRIP1 can promote lymphangiogenesis and lymphatic metastasis development in gastric cancer." (PMID 37409440, 2023). "Oncogene‐like effects of TMEM92‐AS1: LncRNA TMEM92‐AS1 regulates the expression of downstream target gene CCL5 by binding with YBX1 protein to play the role of oncogene and affects prognosis of patients with gastric cancer." (PMID 33247987, 2021). "Aldinucci and Casagrande elaborated on the roles of CCL5 and CCR5 in cell proliferation and metastasis of gastric cancer, and their interaction in regulating immune and inflammatory responses." (PMID 34530822, 2021). "Consistently, a significant positive correlation was found between the expression of CCL5 and CD68 in gastric cancer tissues." (PMID 34638423, 2021). "Oestrogen has been shown to impair CCL5‐ and IL6‐induced gastric cancer cell motility 28, 29, and reduce gastric cancer progression through suppression of erbB‐2 oncogene activation." (PMID 26945908, 2016). "In gastric cancer, CRIP1 interacts with cAMP response element binding protein 1 for transcription to promote the expression of C-C motif chemokine ligand 5 (CCL5), recruit macrophages to promote the secretion of TNF-α, and finally enhance lymphatic permeability to cause tumor cell migration." (PMID 40118853, 2025). "Conversely, TRIM6 depletion in mouse (MTC) and human (MKN28) gastric cancer cells resulted in a significant increase in the mRNA levels of IFNB1 and its downstream genes CXCL10 and ISG15 (or Ccl5) under HT-DNA treatment, and these effects were abolished by simultaneous cGAS knockout." (PMID 40817248, 2025). "Most importantly, either suppressing DNMT enzyme activity, or treatment with demethylation agent, or interfering with CCL5/CCR5/STAT3 pathway led to decreased in vivo tumor growth, suggesting several possible routes of epigenetic inhibition of gastric cancer development." (PMID 30200265, 2018).
gastric cancer (continued). "Interestingly, in a model of gastric cancer, tumor cells induced CD4+ T-cells to secrete CCL5, which in turn, induced apoptosis in CD8+ T cells, while neutralization of CCL5 with monoclonal antibodies induced tumor suppression." (PMID 29559701, 2018). "However, as reported for gastric cancer, TAMs are capable of silencing TSG gelsolin in cancer cells by increased DNMT1 expression and DNA methylation of gelsolin promoter via activation of CCL5/CCR5/STAT3 signaling." (PMID 30200265, 2018). "In TME of gastric cancer, overexpression of cysteine-rich intestinal protein-1 (CRIP1) induces lymphangiogenesis and lymphatic permeability, and then facilitates lymphatic metastasis by upregulating expression of VEGF-C and C-C motif chemokine ligand 5 (CCL5) signaling." (PMID 41511312, 2025). "As shown in previous studies, the VEGF-PIK3/AKT pathway activated by CCL5 promoted tumor metastasis by stimulating angiogenesis and ECM remodeling, and the robust expression of CXCL10 also enhanced gastric cancer invasion and metastasis by binding the receptor CXCR3A." (PMID 35692828, 2022). "Chemokine gene expression signatures including CCL5, CXCL9, CXCL10, and CXCL11 were reported that could accurately predict anti-PD-1 immunotherapy response for patients with head and neck squamous cell carcinoma and gastric cancer." (PMID 32316408, 2020). "In fact, CCL5 and CCR5 are highly expressed in gastric cancer with lymph node metastasis, and CCL5 levels in the lymph nodes with cancer invasion are substantially increased, confirming the role of CCL5/CCR5 axis in metastasis formation." (PMID 24523569, 2014).
colon carcinoma (45 papers, 2011 to 2025). "MALAT1 was also associated with colon cancer progression by stimulating tumor associated dendritic cells (TADC)-derived production of CCL5; consistently, MALAT1 blockade by siRNAs significantly dampened CCL5-induced migration and invasion of CRC cells." (PMID 29739426, 2018). "As CCL5 has been implicated in the interaction between stromal cells and colon cancer cells, we first compared the expression levels of CCL5 in the CM or TCM derived from hMSCs." (PMID 28542126, 2017). "To validate the causative role of paracrine CCL5 in colon cancer progression, we took loss of function approach by using ccl5 siRNAs." (PMID 28542126, 2017). "Moreover, in murine colon tumor models, the CCL5 deficiency within the cancer cells enhances the CD8 T-cell homing into the tumor, thus leading to the delay of both tumor growth and metastasis." (PMID 36429101, 2022). "However, we were unable to detect such effects of walnuts on any metabolic parameters tested, although in HFD+W we did observe a marked reduction in plasma CCL5 levels, and this cytokine has been linked to colon cancer growth and progression." (PMID 29904634, 2018). "In another study on colon cancer and neuroblastoma, the infusion of viruses carrying CCL5 or CCL2 enhanced the number of Th1 infiltrating cells in the TME." (PMID 37631987, 2023). "Among these, CCL5 facilitates the immune escape of colon cancer cells by enhancing the stability of programmed death‐ligand 1 (PD‐L1)." (PMID 36951547, 2023). "In murine colon cancer models, the CCL5 produced by myeloid cells seems to inhibit CD8 T-cell migration, thus favoring tumor growth." (PMID 36429101, 2022). "It was reported that DNA methylation negatively regulates CCL5 expression in lung and colon cancers." (PMID 36352411, 2022). "For example, in colon cancer, tumor derived CCL5 can recruit fibroblasts through the CCR5/SLC25A24 signaling pathway to promote angiogenesis and collagen formation, thereby affecting the tumor microenvironment." (PMID 36033472, 2022). "It has been shown that higher levels of CCL5 expression in human and mouse colon tumor cells promote apoptosis of CD8+ T cells and increase infiltration of regulatory T cells (Tregs)." (PMID 36387070, 2022). "With regard to CCL5‐CCR5 signaling, systemic treatment of mice with CCL5‐directed antibodies inhibit colon cancer growth, lung metastasis, and peritoneal dissemination." (PMID 33463063, 2021). "The CCL5/CCR5 chemokine axis is also capable of enhancing TGF‐β‐mediated killing of cytotoxic CD8+ T cells in colon cancer through regulatory T cells." (PMID 33463063, 2021). "Tumor-derived CCL5/RANTES has been shown to enhance regulatory T cell-mediated killing of cytotoxic T cells in colon cancer." (PMID 34611474, 2021). "Our logistic regression analysis (the area under the curve was 0.958) supports the notion that PDGF-BB, EphA7, and CCL5 are potential biomarkers for the diagnosis of colon cancer." (PMID 31505877, 2019). "Previously, CCL5 expression in human and murine colon cancers was demonstrated to enhance regulatory T cell (Treg) infiltration through CCR5 expression, which can initiate TGF-β-dependent CD8+ T-cell apoptosis." (PMID 31649684, 2019). "Transfected MSCs with sodium iodide symporter and CCL5/RANTES treated mice showed a significant delay in tumor growth after intrasplenic injection of the colon cancer cell line LS174t." (PMID 30533404, 2018). "For the first time, we demonstrated that CCL5 directly induced nuclear accumulation and activation of β-catenin in colon cancer cells." (PMID 28542126, 2017). "Altogether, these results indicate that CCL5/β-catenin/Slug pathway mediates the promotive effect of preactivated-hMSCs on colon cancer progression." (PMID 28542126, 2017). "One of the major findings in this study is that we have identified a novel signaling pathway mediating the paracrine effect of CCL5 on colon cancer cell progression." (PMID 28542126, 2017).
colon carcinoma (continued). "To further determine which receptor on colon cancer cells is responsible for the paracrine effect of CCL5 secreted by hMSCs, we examined the mRNA expression levels of ccr1, ccr3, and ccr5 in SW1116." (PMID 28542126, 2017). "Collectively, these results indicate that CCL5/CCR1 axis plays an important role in preactivated-hMSC-mediated colon cancer progression." (PMID 28542126, 2017). "Collectively, these results suggest that CCL5/CCR1/β-catenin/Slug pathway is responsible for the tumor-promoting effects of TNF-α-activated hMSCs on the development of colon cancer." (PMID 28542126, 2017). "CCL5/RANTES, which is chemotactic for macrophage and T cells, is highly expressed in both human and mouse colon cancers, and contributes to the inflammation and malignant progression." (PMID 26951793, 2016). "CCL5 increases the in vitro growth and the migratory responses of colon cancer cells from both human and mouse origins." (PMID 24523569, 2014). "The CCL5/CCR5 axis plays also a role in colon cancer since CCL5 and its receptors are overexpressed within primary as well as liver and pulmonary metastases compared to healthy tissues." (PMID 24523569, 2014). "Knockdown of CCL5 from CT26 mouse colon tumor cells decreases apoptosis of tumor-infiltrating CD8+ T cells and reduces tumor growth in mice." (PMID 24523569, 2014). "In order to further assess the role of the CCL5/receptors axis in colon cancer, we have looked for a relevant mouse colon carcinoma model." (PMID 22205974, 2011). "The expression of CCL5 receptors by human and murine colon carcinoma cells has led us to determine the ability of their common ligand CCL5 to stimulate their proliferation and migration in vitro." (PMID 22205974, 2011). "To assess the relevance of CCL5/CCR5 neutralization in colon carcinoma, we have used syngeneic experimental models of orthotopic (liver) and ectopic (subcutis) colon cancer in immunocompetent mice." (PMID 22205974, 2011). "Aside from being a promalignant factor acting directly onto colon cancer cells, CCL5 also appeared in our studies as a regulator of inflammatory infiltrates within tumor tissues." (PMID 22205974, 2011). "In vitro, CCL5 increased the growth and migratory responses of colon cancer cells from both human and mouse origins." (PMID 22205974, 2011). "To do so, we have examined a number of human colon cancer clinical specimens and found CCL5 and its receptors over-expressed within primary as well as liver and pulmonary metastases of CRC patients compared to healthy tissues." (PMID 22205974, 2011). "Here, we have assessed the role played by CCL5/CCR5 interactions in the development of colon cancer." (PMID 22205974, 2011). "In summary, our data point to a multiple contribution of CCL5 in colon cancer development, including its ability to promote metastatic features of tumor cells and to dampen anti-tumor immunity." (PMID 22205974, 2011). "CCL5 neutralization resulted in reducing the extent of development of experimental colon tumors implanted into mice either subcutaneously or under the liver capsule, and also led to decrease the peritoneal carcinosis in those mice." (PMID 22205974, 2011). "Additional evidence supporting the involvement of the CCL5/CCR5 axis in colon cancer progression is provided by the antitumor effect of TAK-779, the CCR5 antagonist." (PMID 22205974, 2011). "Next, we used AOM/DSS-induced colon cancer model to determine whether CCL5 and CXCL10 are required for CRC development." (PMID 40749055, 2025). "Moreover, the association of cyclophosphamide with a TLR9 agonist increases the chemokine expression in murine colon tumors (Ccl5, Cxcl9 and Cxcl10) and CD8 T-cell proportion and inhibits tumor growth." (PMID 36429101, 2022). "This supports the idea that CCL5 is a potential biomarker for the diagnosis of colon cancer." (PMID 36387070, 2022).
colon carcinoma (continued). "(2011) showed that CCL5 promotes cell migration and invasion in colon cancer: in vitro experiments showed that treatment of CT26 and HT29 cells with 50 ng/ml of CCL5 determined a 2-fold increase in cell proliferation compared to the controls treated with base medium only (p < 0.01)." (PMID 36059680, 2022). "Meanwhile, CCL5 neutralization renders colon tumors more sensitive to PDGFRβ‐targeted therapy." (PMID 33463063, 2021). "CCL5 is a key chemokine that induces chemotaxis of NK and other immune cells to inflammatory sites and cancer, and CCL5-expressing oncolytic vaccinia virus was shown to promote NK cell infiltration and anti-tumour activity, a xenograft model of colonic cancer." (PMID 34452316, 2021). "Given that Slug is the most upregulated EMT-related transcriptional factor in response to TCM, we sought to test the hypothesis that Slug might be involved in CCL5-mediated colon cancer progression." (PMID 28542126, 2017). "Furthermore,in vivomodel in nude mice confirms the ability of hMSCs to promote the proliferation and progression of colon cancer cells, and the upregulation of CCl5/β-catenin/Slug pathway." (PMID 28542126, 2017). "CCL4 is also a member of the family of beta chemokines that may function in ASPS in ways similar to those observed for CCL5 in colon cancer." (PMID 23226201, 2012). "It is therefore likely that some of the tumor-promoting properties of CCL5 in colon cancer could be mediated through one or two of those additional receptors." (PMID 22205974, 2011). "Given that the anti-CCL5 strategy could only lead to a moderate therapeutic effect against colon cancer, we next sought to evaluate the potential of CCL5 blockade administered in combination with an anti-PDGFRβ strategy." (PMID 22205974, 2011). "In addition, systemic treatment of mice with CCL5-directed antibodies reduced the extent of development of subcutaneous colon tumors, of liver metastases and of peritoneal carcinosis." (PMID 22205974, 2011). "To probe whether the malignancy-related properties of CCL5 exerted onto colon cancer cells in vitro also have a relevance in vivo, we evaluated the impact of CCL5 neutralization on the development of CT26 colon tumors implanted subcutaneously into immunocompetent Balb/c mice." (PMID 22205974, 2011). "In a mouse colon cancer model, the combination of OVT with a chemokine-enhancing cocktail that increased CCL5 and CXCL10 production while reducing CCL22 was demonstrated to boost the trafficking of T helper cells and CTLs to the TME and improve survival." (PMID 37631987, 2023). "The results unraveled that CCL5, THBS, SPP1, ICAM, and TNF signaling pathways were more abundant in colon cancer (red), whereas SELPLG, LIGHT, CSF, and BAFF signaling pathways were more abundant in rectal cancer (green)." (PMID 37675100, 2023). "Our result showed that ccl5 siRNA markedly decreased the TCM-induced upregulation of Slug in SW1116 cells, suggesting that hMSC-induced upregulation of Slug in colon cancer cells is attributed to CCL5 secretion." (PMID 28542126, 2017). "TNF-α-primed-hMSCs secrete high level of CCL5, which interacts with its receptor CCR1 expressed in colon cancer cells." (PMID 28542126, 2017). "Taken together, CCL5/CCR1 axis appears to be crucial in mediating a crosstalk between MSCs and cancer cells to induce colon cancer cell EMT and metastasis." (PMID 28542126, 2017). "To do so, we have analysed by quantitative RT-PCR the expression level of CCL5/CCRs in the human HT29 and in the mouse CT26 colon cancer cells grown in culture." (PMID 22205974, 2011). "Similar to CCL5, CCL3 has also been linked to increased colon tumor development, although, at least to our knowledge, no relevant impact of this CCR5-binding chemokine on the T cell-mediated control of colon cancer has been described so far." (PMID 36428508, 2022).
colon carcinoma (continued). "While CCL5 can bind to CCR1, CCR3, and CCR5, we revealed that the paracrine CCL5-induced cell migration in colon cancer cells was mainly mediated by CCR1, given that CCR1 antagonist completely abolished the increased migration in colon cancer cells in response to CCL5." (PMID 28542126, 2017). "Collectively, these data suggest that CCL5/receptors activation appears as a common feature of the CRC cells from distinct origins and that it could mediate the malignancy-related properties of colon cancer cells." (PMID 22205974, 2011). "Finally, intratumoral administration of CCL5 increased the frequency of CCR5+ CD8+ T cells and mature CD11b+ NK cells within the tumor, and administration of CCL5 plus anti-PD-L1 (atezolizumab) induced tumor growth inhibition over anti-PD-L1 alone in the murine colon tumor model MC38." (PMID 34030676, 2021).